ABCC1 (ATP binding cassette subfamily C member 1 (ABCC1 blood group))
Diseases named in the same sentence as ABCC1 in open-access papers (continued):
Sharing a sentence is not in itself a finding about the gene and the disease.
triple-negative breast carcinoma (7 papers, 2019 to 2024). An invasive breast carcinoma which is negative for expression of estrogen receptor (ER), progesterone receptor (PR), and human epidermal growth factor receptor 2 (HER2). "Previous studies reported that MDR1 (ABCB1) and ABCC1 (MRP1) expressions in breast cancer are subtype-specific and associated with triple-negative breast cancer." (PMID 37239055, 2023). "ZEB1-AS1 promotes triple-negative breast cancer resistance to doxorubicin through miR-186-5p/ABCC1 signaling." (PMID 36246627, 2022). "Targeting ABCB1 and ABCC1 with tariquidar may be a promising strategy for reversing the acquired multidrug resistance of triple-negative breast cancer cells." (PMID 34208283, 2021). "The other CoREST complex member, LSD1, was reported to repress ABCC1 and ABCC10 gene expression upon inhibition of EP300 in the triple-negative breast cancer cell line MDA-MB-231." (PMID 35205642, 2022).
Alzheimer disease (6 papers, 2012 to 2022). A progressive, neurodegenerative disease characterized by loss of function and death of nerve cells in several areas of the brain leading to loss of cognitive function such as memory and language. "In animal models of Alzheimer’s disease, the long-term deficiency of ABCB1 and ABCC1 has previously been found to accelerate neurodegeneration as a consequence of reduced β-amyloid elimination." (PMID 31572128, 2019). "Recently, ABC transporters have been discovered to exhibit important export functions for proteins involved in Alzheimer's disease, with ABCC1 being of exceptional importance for the clearance of β-amyloid from the brain." (PMID 22545122, 2012). "Several ABC transporters, including ABCA1, MDR1/ABCB1, MRP1/ABCC1, ABCG2, and ABCG4, have been implicated in the pathogenesis of Alzheimer’s disease (AD), a progressive neurodegenerative disorder characterized by the deposition of amyloid-β (Aβ) peptides in the brain." (PMID 33801813, 2021). "Interestingly, ABCC1 has been discovered recently to play an important role in the excretion of toxic Aβ peptides in Alzheimer's disease models via the brain's barriers." (PMID 22545122, 2012). "Increasing ABCC1 expression or activity may prevent or attenuate Alzheimer's disease symptoms." (PMID 32878879, 2021). "In a talk on sporadic proteopathies of the brain, Markus Krohn from Jens Pahnke`s group in Magdeburg reported on the role of ABC transporters in Alzheimer`s disease with a special focus on the effect of ABCB1 and ABCC1 regarding clearance mechanisms." (PMID 24330587, 2013). "In models of Alzheimer’s disease, concerns have been raised that the long-term inhibition of ABCB1 and ABCC1 may exacerbate neurodegeneration as a consequence of reduced β-amyloid clearance." (PMID 31572128, 2019).
breast tumors (6 papers, 2014 to 2025). "Those patients, who had ERα-positive breast tumors with low expression of Nrf2, ABCC1, ABCC3 and NQO1 at the time diagnosis, had a better prognosis after tamoxifen treatment than those patients that were high expressers, with an HR value as high as 4.2." (PMID 26883574, 2016). "Since prior studies have shown that bile acids can inhibit ABCC1-mediated transport of chemical agents in erythrocytes, we first assessed whether β-cholanic acid could also enhance drug accumulation into breast tumour cells." (PMID 29615646, 2018). "Thus, evaluating breast tumors of patients for the expression of Nrf2, ABCC1, ABCC3 and NQO1 warrants formal assessment as predictive markers for tamoxifen response." (PMID 26883574, 2016). "In conclusion, according to our present data, SNPs rs35623 and rs35628 in non-coding regions around NBD1 may modulate ABCC1 transcript levels in breast tumors, thus contributing to a complex pattern of chemotherapy resistance by so far unknown mechanism." (PMID 25078270, 2014). "To confirm that ABCC1 is a biomarker for T-DXd and not simply prognostic, we leveraged a large cohort of breast tumors with ABCC1 expression and outcome data." (PMID 41422323, 2025). "Additionally, high levels of expression of Nrf2, ABCC1, ABCC3 plus NAD(P)H dehydrogenase quinone-1 in breast tumors of patients at the time of diagnosis were prognostic of poor survival after tamoxifen therapy." (PMID 26883574, 2016).
epilepsy (6 papers, 2014 to 2025). A brain disorder characterized by episodes of abnormally increased neuronal discharge resulting in transient episodes of sensory or motor neurological dysfunction, or psychic dysfunction. "The screening of SNPs in ACBC1 and ABCC2 indicates that the Mexican patients with epilepsy in this study display frequently reported ABCC1 polymorphisms; however, in the study subjects with a higher risk factor for drug resistance, new nucleotide changes were found in the ABCC2 gene." (PMID 25346718, 2014). "ABCB1 and ABCC1 have been detected in human tissue samples of focal cortical dysplasia and benign tumor lesions in therapy-refractory epilepsy patients." (PMID 38727275, 2024). "In drug-resistant epilepsy patients, the overexpression of ABCB1 and ABCC1 was found on reactive astrocytes and the overexpression of ABCB1-3 and ABCC4 was detected on endothelial cells." (PMID 38727275, 2024). "ABCB1, but also ABCC1, ABCC2, and ABCC5, expression is increased in brains from medically intractable epilepsy patients, hinting at their role in the resistance to treatments." (PMID 38727275, 2024).
liver cancer (6 papers, 2018 to 2025). An epithelial or non-epithelial malignant neoplasm that arises from the liver. "We observed that the expression of ABCC1 and ABCC5 was associated with the prognosis of liver cancer in both data sets." (PMID 35342392, 2022). "Furthermore, compared to other ABC transporters like ABCC1 and ABCC4, ABCC5 more directly reflects HCC progression and drug resistance, making it highly valuable for precision medicine and targeted therapies in liver cancer." (PMID 40860808, 2025).
lung adenocarcinoma (6 papers, 2017 to 2025). A carcinoma that arises from the lung and is characterized by the presence of malignant glandular epithelial cells. "In lung adenocarcinoma, circ-PVT1 overexpression is involved in chemoresistance through the miR-145-5p/ABCC1 axis." (PMID 36358938, 2022).
asthma (5 papers, 2018 to 2025). "HTR2C, CYP1B1, CYP19A1, ESR1, ESR2, PDR, and AR are found to be interrelated to hormonal disorders; ABCC1, NQO1, TIMP1, ADRB2, and ALOX5 are associated with asthma." (PMID 29861771, 2018). "In a previous study that analyzed the expression of 48 known ABC transporters in smokers with and without COPD as well as asthma diagnosis, three of them, ABCB6, ABCC1, and ABCC3, were shown to be upregulated by exposure to cigarette smoke." (PMID 38442133, 2024).
cervical cancer (5 papers, 2016 to 2025). A primary or metastatic malignant neoplasm involving the cervix. "Therefore, THC may also be a potential MDR reversal agent with the function of modulating the three-drug transporters ABC: ABCB1, ABCG2, and ABCC1 in human cervical cancer." (PMID 39598712, 2024). "In vincristine-resistant human cervical carcinoma (KB-vin) cells, characterized by high ABCB1 mRNA expression and minimal expression of ABCC1 and ABCG2, β-carotene (100 μM) significantly upregulated ABCB1 mRNA levels." (PMID 41303640, 2025). "Promoter methylation of ABCB1, ABCC1, and ABCG2 has been determined in the cervix cancer line KB-3-1 and two drug-resistant sublines, KBC-1, selected against colchicine and overexpressing ABCB1, and KB-1089, selected against the thiosemicarbazone KP1089 and overexpressing ABCC1 and ABCG2." (PMID 33066132, 2020).
chronic myeloid leukemia (5 papers, 2020 to 2025). "Recently, a genome-wide CRISPR/Cas9 screen in the human chronic myeloid leukemia cell line K562 identified ABCC1, SLC30A1, and AQP3 as important regulators of arsenic toxicity." (PMID 39578074, 2025). "Indeed, glycosphingolipid biosynthesis was shown to regulate drug sensitivity in clinically relevant models of drug-resistant chronic myeloid leukemias, through modulation of both the expression and activity of the drug efflux proteins ABCB1 and ABCC1." (PMID 36983080, 2023).
epidermoid carcinoma (5 papers, 2013 to 2024). "As KB-3-1 is a human epidermoid carcinoma cell line, it is possible that, to some extent, developing other mechanism induces drug resistance apart from ABCC1 overexpression in the KB-CV60 cell line." (PMID 33718236, 2021). "However, the drug resistance of ABCC1/MRP-overexpressing epidermoid carcinoma cells was found to be due to both reduced drug accumulation and Bcl-xS expression during apoptotic cell death." (PMID 38473345, 2024). "We found that in immortalized human keratinocytes and in squamous cell carcinoma (SCC) cells, ∆Np63 induces the expression of ABCC1 by physically occupying a p63-binding site (p63 BS) located in the first intron of the ABCC1 gene locus." (PMID 39201428, 2024).
neutropenia (5 papers, 2011 to 2025). A decrease in the number of neutrophils found in the blood. "The reduced function variant, rs17501331, in the ABCC1 gene is associated with low incidence of neutropenia; the reverse effect was detected with the GOF variant rs6498588 in the same gene." (PMID 31792369, 2020). "We reported a higher risk of recurrent neutropenia in carriers of ABCC1 rs212091 genotype AG." (PMID 39596349, 2024). "With regard to NLE (the secondary study aim), the study reported that rs4148350 and rs246221 in ABCC1 and rs76688282 in UGT2B7 were significantly associated with prolonged grade 3–4 or deep neutropenia." (PMID 29100455, 2017).
Hypertension (4 papers, 2013 to 2024). The presence of chronic increased pressure in the systemic arterial system. "Among the common DEGs that most significantly changed the transcription level during stress, two genes (Abcc1 and Nos1) associated with hypertension deserve the most attention." (PMID 39594444, 2024). "In particular, when analyzing both rat strains, a high correlation of Abcc1 and Nos1 expression was shown with the expression of the transcription factor gene Arnt associated with hypertension." (PMID 39594444, 2024). "Moreover, hypertension-associated endothelial dysfunction was ameliorated in ABCC1-deficient mice in vivo." (PMID 28383515, 2017). "The hypertension-associated genes Nos1 and Abcc1 are downregulated in the hypothalamus of both rat strains, and Cyp1b1 and Fos are ISIAH-specific DEGs associated with hypertension." (PMID 39594444, 2024). "Moreover, ABCC1 has been related to hypertension, modulating endothelial cell oxidative stress and it is known that this protein plays a critical role in the hypertensive response to angiotensin II." (PMID 23840808, 2013). "ABCC1 may contribute to the occurrence and progression of cardiovascular diseases, and the inhibition of ABCC1 may represent a new strategy for the prevention of hypertension, endothelial dysfunction, and atherosclerotic vascular disease in high-risk patients with cardiovascular diseases." (PMID 34201488, 2021). "Taken together, ABCC1 might contribute to the onset and progression of CVD, and ABCC1 inhibition may represent a novel strategy to prevent hypertension, endothelial dysfunction and atherosclerotic vascular disease in high-risk cardiovascular patients." (PMID 28383515, 2017).
Obesity (4 papers, 2018 to 2024). Accumulation of substantial excess body fat. "It has been found that tissue corticosterone concentrations in human adipose tissue are persistently low but ABCC1 mRNA is upregulated in obesity." (PMID 39594522, 2024). "Our findings of a novel role for ABCC1 in limiting the adverse metabolic effects of obesity should stimulate further investigation of the various substrates of ABCC1 and their transmembrane transport in obesity." (PMID 38829241, 2024). "Here, we investigate the impact of Abcc1 deficiency on glucocorticoid action and high-fat-diet (HFD)-induced obesity." (PMID 38829241, 2024). "The positive correlation of genes such as HSD11B1, PTPN22, ABCC1, MMP9, FGF1, and F13A1 with M0 and M1 macrophages suggests a possible role in shaping the immune response toward a more beneficial phenotype in obesity." (PMID 39594522, 2024). "Importantly, the role of Abcc1 in murine models of obesity has not yet been described." (PMID 38829241, 2024).
renal carcinoma (4 papers, 2022 to 2023). A carcinoma arising from the epithelium of the renal parenchyma or the renal pelvis. "Downregulation of miR-210-3p (downregulated in MNR) has been related to an increase in ABCC1 expression in renal carcinoma and a subsequent reduction in chemotherapy drug sensitivity." (PMID 36768211, 2023). "Finally, ABCC1/MRP1 was found as an effective transporter of imatinib from chronic myeloid leukemia (CML) cells, whereas sorafenib was proposed as a substrate for ABCC2/MRP2, therefore causing sorafenib resistance of renal carcinoma cell lines in vitro." (PMID 35327403, 2022).
schizophrenia (4 papers, 2009 to 2025). A major psychotic disorder characterized by abnormalities in the perception or expression of reality. "Beyond their pharmacokinetic influence, both ABCB1 and ABCC1 participate in glutathione-dependent detoxification and oxidative stress responses—pathways strongly implicated in the neurobiology of schizophrenia." (PMID 41465144, 2025). "Analysis of the ABCC1 gene expression revealed differences in people with schizophrenia relative to healthy controls." (PMID 41465144, 2025). "Our findings revealed significant downregulation of ABCC1 in the acute, antipsychotic-free phase of schizophrenia." (PMID 41465144, 2025). "Dysregulation of transporters such as ABCC1, ABCB1, and ABCA2 has been linked to neuropsychiatric disorders, yet their expression patterns in schizophrenia and their modulation by antipsychotic treatment remain unclear." (PMID 41465144, 2025). "All three deletions included the region chr16:15387380–16198600 (and the genes MPV17L, c16orf45, KIAA0430, NDE1, MYH11, KIAA0866, c16orf63, ABCC1 and MRP6/AbCC6) indicating that a large deletion of this region may be a recurrent schizophrenia risk factor." (PMID 19197363, 2009). "Collectively, these findings underscore the potential gene-specific heterogeneity of ABC transporter biology in schizophrenia: ABCC1 may relate to inflammatory variability, ABCB1 may reflect pharmacodynamic differences, and ABCA2 may index treatment-associated metabolic adaptations." (PMID 41465144, 2025). "The present study aims to address this gap by examining the longitudinal expression patterns of ABCC1, ABCB1, and ABCA2 in individuals with schizophrenia before and after antipsychotic treatment, and by comparing these patterns with those of healthy controls." (PMID 41465144, 2025). "We did not detect a change in either ABCB1 or ABCC1 expression in people with schizophrenia nor in the context of high inflammation, which is in keeping with the fact that ABCB1 expression is only slightly reduced by IL-6 and increased by TNFα." (PMID 30214039, 2020).
viral infection (4 papers, 2021 to 2024). "We found that protein levels of endogenous ABCC1 were unchanged upon virus infection in our setting." (PMID 38652659, 2024). "Moreover, the ATP-binding cassette, subfamily C protein ABCC1 has first-degree interactions with both 3CLpro and luteolin, indicating that ABCC1 is important for viral infection." (PMID 39045772, 2024). "In addition, HSV-1 inhibited RA synthesis, thereby preventing the decline in ABCC1 induced by viral infection." (PMID 38989466, 2024). "By the way, another ABC transporter Abcc1 gene expression was not affected in liver, lung, and e-WAT tissues by the virus infection." (PMID 34635791, 2021).
chronic obstructive pulmonary disease (3 papers, 2015 to 2024). A chronic and progressive lung disorder characterized by the loss of elasticity of the bronchial tree and the air sacs, destruction of the air sacs wall, thickening of the bronchial wall, and mucous accumulation in the bronchial tree. "Recent genomic studies have identified certain ABCC1 polymorphisms associated with a greater/lesser severity of chronic obstructive pulmonary disease (COPD)." (PMID 37438132, 2023).
colon adenocarcinoma (3 papers, 2020 to 2024). "Our findings showed a significantly increased expression of ABCC1 in breast invasive carcinoma and colon adenocarcinoma compared with their respective normal samples." (PMID 39123364, 2024). "The circadian expression of Abcc1 was studied in the Caco-2 cell line (derived from human colon adenocarcinoma) with a peak between the 6th and the 12th hour after synchronization." (PMID 35269592, 2022).
multiple myeloma (3 papers, 2014 to 2022). "In multiple myeloma patients treated with bortezomib, alterations in PSMB1, encoding drug binding proteins, and ABCC1 and ABCC6, encoding drug transport, were also associated with CIPN." (PMID 35360655, 2022).
renal cell carcinoma (3 papers, 2009 to 2021). "In this retrospective study the expression of two of these transporter efflux pumps, namely MDR-1 P-gp (ABCB1) and MRP-1 (ABCC1) were studied by immunohistochemistry in archival material from 95 renal cell carcinoma patients." (PMID 19552816, 2009). "ATP-binding cassette transporter super-family including ABCC1 and MDR-1 were involved in multi-drug resistance (MDR) of renal cell carcinoma (RCC) patients." (PMID 29445446, 2018). "In renal cell carcinoma (RCC) and colon cancer cell lines exhibiting MDR and augmented ABCB1 expression, we have identified PITX2 as a contributor to chemotherapeutic drug resistance through transcriptional upregulation of ABCB1 as well as ABCC1, ABCG2, and the drug uptake transporter, SLC22A3." (PMID 35582031, 2021).
atherosclerosis (2 papers, 2020 to 2021). A disease characterized by the build-up of fatty material and calcium deposition in the arterial wall resulting in partial or complete occlusion of the arterial lumen. "ABCC1 is found in large quantities in vascular smooth muscle cells, which make up the majority of vascular wall cells and are involved in the process of atherosclerosis." (PMID 34201488, 2021). "The participation of ABCC1 in the pathogenesis of atherosclerosis is currently the subject of active research." (PMID 34201488, 2021). "Thus, ABCC1 demonstrates involvement in the development of COPD and atherosclerosis." (PMID 34201488, 2021).
autoimmune disease (2 papers, 2023 to 2026). A disorder resulting from loss of function or tissue destruction of an organ or multiple organs, arising from humoral or cellular immune responses of the individual to their own tissue constituents. "Previous studies have revealed the influence of various SNPs on the toxicity of MTX in patients with autoimmune diseases, such as MTHFR, MTR, ABCC1, ABCC2, and ABCG2." (PMID 37761008, 2023).
brain tumors (2 papers, 2019 to 2021). "ABC transporter inhibitors, including ABCB1 and ABCC1 inhibitors, have already been studied in brain tumors in clinical trials." (PMID 31572128, 2019).
COVID-19 (2 papers, 2020 to 2021). A disease caused by infection with severe acute respiratory syndrome coronavirus 2. "Based on their important role in tissue barriers and drug pharmacokinetics, we studied the potential inhibition of the function of ABCB1, ABCG2, ABCC1, OATP2B1, and OATP1A2 by the clinically applied anti-COVID-19 agents." (PMID 33435273, 2021).
cystic fibrosis (2 papers, 2017 to 2023). Autosomal recessive disorder caused by pathogenic variants in the CFTR gene (cystic fibrosis transmembrane conductance regulator), which encodes a chloride and bicarbonate channel expressed in epithelial cells, and follow the diagnosis criteria. "Upregulation of ABCC1 is thought to improve lung function in patients with cystic fibrosis; the mechanism underlying this effect is unknown." (PMID 28800122, 2017).